ENSG00000206878
Synonyms: LOC124900442
Gene: Small nucleolar RNA gene on chromosome 1 (228,652,436 to 228,652,560, forward strand). Ensembl gene ENSG00000206878.
Gene Ontology:
Biological process: RNA processing
Cellular component: nucleolus
Homologues: Paralogues in human: SNORA51 (87% identical).